TBC1D31 (TBC1 domain family member 31)
Description:
Molecular adapter which is involved in cilium biogenesis. Part of a functional complex including OFD1 a centriolar protein involved in cilium assembly. Could regulate the cAMP-dependent phosphorylation of OFD1, and its subsequent ubiquitination by PJA2 which ultimately leads to its proteasomal degradation.
Synonyms: WDR67; MGC21654; Gm85
Tractability: PROTAC: ubiquitination databases record sites on it.
Gene: Protein-coding gene on chromosome 8 (123,041,968 to 123,152,154, forward strand). Ensembl gene ENSG00000156787.
Subcellular location: Cytoplasm, cytoskeleton, microtubule organizing center, centrosome; Cytoplasm, cytoskeleton, microtubule organizing center, centrosome, centriolar satellite; Cytoplasm, cytoskeleton, cilium basal body
Subcellular location (Human Protein Atlas): Basal body; Centrosome
Gene Ontology:
Molecular function: molecular adaptor activity; protein binding
Biological process: cilium assembly
Cellular component: centriolar satellite; centrosome; ciliary basal body
Genetic constraint (gnomAD): Loss-of-function variants: 66 observed, 92.08 expected, observed/expected ratio (o/e) 0.72, 90% interval 0.59 to 0.88. The upper end of that interval is the gene's LOEUF score, 0.88, which puts it in group 3 of 6, group 1 being the genes least tolerant of losing a copy. Missense variants: 898 observed, 1,023.9 expected, observed/expected ratio (o/e) 0.88, 90% interval 0.83 to 0.93. Synonymous variants: 324 observed, 348.1 expected, observed/expected ratio (o/e) 0.93, 90% interval 0.85 to 1.02.
Homologues: Orthologues: chimpanzee TBC1D31 (99% identical), rabbit TBC1D31 (88% identical), dog TBC1D31 (88% identical), pig TBC1D31 (86% identical), guinea pig TBC1D31 (85% identical), rat Tbc1d31 (81% identical), mouse Tbc1d31 (79% identical), tropical clawed frog tbc1d31 (63% identical), zebrafish tbc1d31 (56% identical), Drosophila melanogaster CG16896 (23% identical), Caenorhabditis elegans F13H8.2 (12% identical). Paralogues in human: WDR3 (15% identical).
Diseases named in the same sentence as TBC1D31 in open-access papers:
TBC1D31 is named in the same sentence as 10 diseases in open-access papers, as found by Europe PMC text mining. Sharing a sentence is not in itself a finding about the gene and the disease. The quoted sentences say what the papers report.
ovarian carcinoma (1 paper, 2024). A malignant neoplasm originating from the surface ovarian epithelium. "This strategy may also be promise for the treatment of other types of cancer characterized by frequent amplification of TBC1D31 (> 50%), such as uveal melanoma, ovarian cancer, and uterine carcinosarcoma." (PMID 39206796, 2024).
tumor (5 papers, 2010 to 2024). "Multivariate logistic regression analysis identified SNPs in 2 genes (Plxna2 and Tbc1d31) that were independently associated with tumour metastasis." (PMID 39067134, 2024). "We pooled all 20 genes (Stx6, Ramp1, Traf3ip1, Nckap5, Pfkfb2, Trmt1l, Rprd1b, Rer1, Sepsecs, Rhobtb1, Tsen15, Abcc3, Arid5b, Tnr, Dock2, Tti1, Fam81a, Oxr1, Plxna2 and Tbc1d31) together as the mouse tumour susceptibility gene signature (mTSGS)." (PMID 39067134, 2024). "Intriguingly, we observed significantly higher TBC1D31 expression in liver portal vein tumor thrombus (PVTT) tissues than in their counterpart primary HCC tissues." (PMID 39206796, 2024). "Taken together, these findings support the 8q24.13 gain‐driven upregulation of TBC1D31 as a common event in tumor progression with prognostic value." (PMID 39206796, 2024). "Knockdown of TBC1D31 in HCCLM3 cells led to a significant decrease in the subcutaneous tumor volume and weight in mice." (PMID 39206796, 2024). "Conversely, TBC1D31 overexpression in HepG2 cells significantly promoted tumor growth, with the pro‐proliferative effect indicated by increased expression of Ki‐67." (PMID 39206796, 2024). "Accordingly, the tumor growth inhibition rates of the lenvatinib‐treated and TBC1D31‐knocked‐down groups were 25% and 47%, respectively, while the combined treatment group increased to 75%." (PMID 39206796, 2024). "The immunohistochemistry (IHC) analyses showed overexpressed protein levels of TBC1D31 in HCC tissues compared with non‐tumor liver tissues from the VALI cohort (n = 168), which also correlate with the 8q24.13 copy numbers." (PMID 39206796, 2024). "CDCA7, CELSR3, PACS1, SNTB1, and TBC1D31 showed consistent upregulation in CRC tumor samples and pre-surgical cfRNA, while GFI1B, HPGD, SH3BGRL2, SIAE, PKHD1L1, and TDP2 showed downregulation in CRC tumor samples and pre-surgical cfRNA." (PMID 37091184, 2023). "Multivariate analyses flagged SNPs in 20 genes (Stx6, Ramp1, Traf3ip1, Nckap5, Pfkfb2, Trmt1l, Rprd1b, Rer1, Sepsecs, Rhobtb1, Tsen15, Abcc3, Arid5b, Tnr, Dock2, Tti1, Fam81a, Oxr1, Plxna2, and Tbc1d31) independently tied to various tumour characteristics, designated as a mTSGS." (PMID 39067134, 2024). "The significant increases in TBC1D31 mRNA expression in tumor tissues relative to the match non‐tumor tissues were also observed in multiple types of cancer from the TCGA pan‐cancer cohorts, and their fold‐changes were significantly correlated with the frequencies of 8q24.13 gain." (PMID 39206796, 2024). "Moreover, we also assessed the effects of TBC1D31 on sensitivity to lenvatinib in the patient‐derived primary tumor cells (PDCs) isolated from the both models." (PMID 39206796, 2024). "Additionally, three datasets from the mouse HCC models (including the diethylnitrosamine [DEN]‐induced, CCl4‐induced and HBV transgenic models) consistently showed a significant increase in the expression of Tbc1d31 in liver tumors compared to non‐tumor livers." (PMID 39206796, 2024). "Further, we found that the male or tumor capsule‐free patients, or those with advanced TNM stage, respectively, exhibit significantly higher TBC1D31 expression levels compared to the respective other patients in VALI cohort." (PMID 39206796, 2024). "Knockdown of TBC1D31 in HCCLM3 cells significantly reduced the lung metastasis burden, which consequently resulted in a prolonged survival period of the tumor‐bearing mice." (PMID 39206796, 2024). "Consistently, IHC assays showed that TBC1D31 protein levels are significantly positively correlated with the levels of EGFR, p‐EGFR, p‐ERK1/2 and p‐AKT in subcutaneous tumor tissues from nude mice, and the HCC tissues from the VALI cohort (n = 168)." (PMID 39206796, 2024).
cancer (2 papers, 2024). A tumor composed of atypical neoplastic, often pleomorphic cells that invade other tissues. "Consistently, by examining the co‐dependencies of TBC1D31 in the genome‐wide shRNA screening database of 600 cancer cell lines, we found significant enrichment of “Internalization of ErbB1 (EGFR)” by dependent genes." (PMID 39206796, 2024). "Accordingly, higher levels of TBC1D31 protein were observed in multiple types of cancer indexed in the HPA database." (PMID 39206796, 2024). "Again, TCGA pan‐cancer analyses showed that higher TBC1D31 mRNA levels are correlated with the advanced clinical stages, and poor OS or DFS rates in patients with several other types of cancer." (PMID 39206796, 2024).
TBC1D31 also shares sentences with these, for which no sentence is quoted: colorectal cancer (1 paper); hepatocellular carcinoma (1); microcephaly (1); microphthalmia (1); nephrotic syndrome (1); uterine carcinosarcoma (1); uveal melanoma (1).